IGF1R (insulin like growth factor 1 receptor)
Diseases named in the same sentence as IGF1R in open-access papers (continued):
Sharing a sentence is not in itself a finding about the gene and the disease.
cancer (continued). "The first one is that HER2-positive human cancer cells usually co-express IGF1R." (PMID 30979001, 2019). "In addition, miR-615 and miR-1251 jointly targeted IGF1R (insulin-like growth factor 1 receptor) and participated in the reproductive process of cancer cells through phosphoinositide 3-kinase-Akt pathway and the shc-ras-MAPK pathway." (PMID 31885571, 2019). "By considering the target effect of miR-486 on the IGF-1R in cancer, the hypothesis that miR-486 contributes to the development of cancer in patients with DM, directly or indirectly by the IGF axis, is reasonable." (PMID 31847392, 2019). "Simulations of our models could provide a rationale for selecting targets in the network that are more likely to be successful for treating cancers driven by IGF1R signaling." (PMID 30653502, 2019). "This review explores this emerging paradigm with respect to the cancer-relevant insulin-like growth factor type 1 receptor (IGF-1R) and discusses how this perspective could inform future targeting strategies." (PMID 31600876, 2019). "The IGF1R signaling is important in the malignant progression of cancer." (PMID 31267557, 2019). "Cancer cells may therefore be able to circumvent IGF1R inhibition by upregulating another or several RTKs." (PMID 31179642, 2019). "All of these proteins are over-expressed in different types of cancer (breast, prostate, lung, gastric, etc) and correspond, for example, to the insulin-like growth factor 1 receptor, the macrophage-stimulating protein receptor and the aurora kinase B, among others." (PMID 31261733, 2019). "Therefore, the IGF-1R pathway is a key mediator of cancer cell growth and cancer resistance to commonly used therapeutics." (PMID 31113478, 2019). "Hence, miRNAs and lncRNAs are regarded as attractive potential biomarkers for diagnosis and therapeutic targets in DMs and cancer through the regulation of IGF-1R." (PMID 31847392, 2019). "Both Igf1r and Map3k5 were related to cancer and metabolism." (PMID 31484384, 2019). "In addition to sharing of IGF1R and CAMKIIA in HIF-1 signaling pathway in our enriched cancer stemness pathways, high IGF1R and CAMKIIA expression enhances the carcinogenesis by inducing the stemness, chemoresistance and anti-apoptosis." (PMID 30944375, 2019). "However, there are multiple lines of evidence to suggest that cancers can use the INSR/IGF1R pathway as a resistance mechanism to other treatments and that IGF1R inhibition can augment responses to standard chemo‐ and radiotherapy." (PMID 31179642, 2019). "Indeed, IGF/IGF-1R expressions are negatively correlated with 5-year overall survival in several types of cancer." (PMID 31467485, 2019). "So IGF1R can be regarded as one of target sites in cancer treatment." (PMID 31033359, 2019). "Among the genes obtained from screening results, we noticed that a cancer-related gene, IGF1R, might be a tentative target of miR-30a-5p whose 3’-UTR contains two putative miR-30a-5p seed sites." (PMID 29642855, 2018). "These cancers share two major IGF-1R signaling transduction pathways, PI3K/AKT and RAS/MEK/ERK." (PMID 30111747, 2018). "Overexpression of the IGF1R gene constitutes a typical feature of most human cancers." (PMID 29455671, 2018). "In previous studies, several miRNAs, such as miR-711, miR-12212, miR-13913 and miR-37514 have shown therapeutic potential that can delay the progression and development of certain human cancers by epigenetically interfering of primary signalling by targeting IGF-1R." (PMID 29712908, 2018). "In certain cancer types, the altered IR isoform expression may play a more important role than the IGF-1R itself." (PMID 30453495, 2018). "Total IGF1R expression was up-regulated in cancer tissue compared to healthy tissue." (PMID 29662006, 2018).
cancer (continued). "When we evaluated protein expression on cancer tissues, the data confirmed the same trend (Cuzick z = +3.05, p = 0.002 for IGF1R and z = −3.60, p = 3 × 10−4 for phospho-protein) and also showed an increased expression of total ERK1/2 (Cuzick z = +3.04, p = 0.002) across the groups." (PMID 29662006, 2018). "IR isoform expression in cancers may have the meaning of a predictive biomarker and co-targeting IGF-1R and IR-A may represent a new more efficacious treatment strategy." (PMID 30453495, 2018). "From a clinical point of view, the IR-A overexpression in cancer may be a determinant factor for the resistance to IGF-1R target therapies for this issue." (PMID 30453495, 2018). "Although the first results of the clinical trials with compounds that target insulin/IGF signaling in PDAC have been disappointing, researchers have recently directed their research towards understanding the role of Insulin/IGF-1R signaling in the cross-talk between cancer cells and stroma." (PMID 29475434, 2018). "The cancer-promoting effect of hyperinsulinemia is based on the knowledge that insulin has both metabolic and mitogenic actions via its own receptor in addition to the IGF-1R, which is activated by insulin with a much lower affinity." (PMID 30453495, 2018). "TSN inhibits the proliferation of various types of cancer cells but its role in the IGF-1R-induced proliferation of pheochromocytoma (PC12) cells and the potential mechanisms are largely unknown." (PMID 30213025, 2018). "IGF1R exhibits anti-apoptotic, pro-survival activities, and is regarded as a key player in cancer." (PMID 29455671, 2018). "Based on previous reports, surviving dormant cancer cells may over-express insulin-like growth factor-1 receptor (IGF-1R) during recurrence and Axl may mediate different signals in high and low glucose situations." (PMID 30419905, 2018). "In conclusion, novel anti-cancer therapeutic strategies should be established for a new therapeutic approach, including the inhibition of the IR-A overexpression, the increased IR-A:IR-B and the IR-A/IGF-1R expression in cancer cells." (PMID 30453495, 2018). "Importantly, MP subtype cancer cells are more sensitive to inhibition of IGF1/IGF1R pathway than EP subtype." (PMID 29725014, 2018). "Therefore, efforts are being made to develop agents that target IGF-1R for cancer treatment, and several such drugs have been assessed in clinical trials." (PMID 28046018, 2017). "In particular, it is now well accepted that IR and its homolog IGF-1R are functionally interconnected by forming hybrid receptors with an important role in cancer, and that targeting either IR or IGF-1R alone results in increased activity of the homolog receptor and resistance to treatment." (PMID 29184536, 2017). "Extensive molecular profiling revealed that a number of components of the IGF pathway, including IRS2 and IGFBP5, may play key roles in determining the sensitivity of cancer cells to humanized IGF1R antibody figitumumab." (PMID 28706506, 2017). "However, the conclusion of later clinical trials revealed a dim future for IGF-1R inhibitors to treat cancer." (PMID 28427155, 2017). "The complexity of IGF signaling may be one of the reasons for the failure of IGF-1R-targeted agents in clinical trials involving many types of cancers." (PMID 28046018, 2017). "Some other studies also demonstrated that miR-7 can regulate the occurrence of various cancers through repressing its target genes like EGFR (epidermal growth factor receptor), ACK1 (Activated Cdc42-associated Tyrosine Kinase 1), or IGF1R (insulin-like growth factor 1 receptor)." (PMID 28210621, 2017). "Recent studies implied a pivotal function of IGF1R signaling in cancer progression." (PMID 28572530, 2017). "Given the important role of the IGF1R in mitogenesis, the present results may be of translational relevance in cancer research." (PMID 28945762, 2017).
cancer (continued). "Interestingly, IGF-1R expression is also high in differentiated cancers but decreases somehow with cancer dedifferentiation." (PMID 29184536, 2017). "We also found IGF1R expression in one HDB sample suggesting that the IGF1R expression could possibly come from non-cancer cells." (PMID 28489591, 2017). "The reported clinical evidence indicates that T2E, with its wide spectrum of alterations, may counteract the putative beneficial effects conferred by IGF-1R expression, likely addressing cancer cells toward a less differentiated, more aggressive phenotype." (PMID 28545426, 2017). "In cancer cells, the synergistic effect induced by enhanced E2F and mTOR activities changed the gene expression of some components in cell proliferation/survival signaling, such as Bcl2l1 and insulin-like growth factor 1 receptor (Igf1r)." (PMID 28076433, 2017). "In view of the double-sided effects of autophagy in cancer, we set forth to investigate whether IGF-1R inhibition-induced autophagy is beneficial to TNBC cells." (PMID 28046018, 2017). "We conducted this analysis to figure out how IGF-1R inhibitors acted in clinical cancer therapy." (PMID 28427155, 2017). "Hence, targeted therapies against the IGF1R (particularly blocking antibodies and tyrosine kinase inhibitors) emerged in recent years as a promising therapeutic approach in cancer treatment." (PMID 28945762, 2017). "As an anti-cancer target, IGF1R has become an attractive target for novel cancer therapeutics." (PMID 28521298, 2017). "Indeed, treatment with ONC201 or ONC212 in combination with the IGF1-R specific inhibitor AG1024 resulted in a synergistic anti-cancer effect and initiation of apoptosis in PANC-1 cells that survived each drug alone." (PMID 29137221, 2017). "In some preclinical models of cancer, IGF1R antibody is showing promise." (PMID 29212217, 2017). "The relevance of the IGF system and particularly IGF-1R in cancer has been widely documented." (PMID 28545426, 2017). "Oncogenic signalling through IGF1R tyrosine kinase has become a major focus of cancer research." (PMID 28793874, 2017). "To further explore the role of IGF1R signaling pathway in the anti-cancer activity and EMT modulation of phenformin, we examined the specific effects of phenformin on IGF1-induced proliferation, RTK signaling, and the alteration of EMT markers in SKBR3 and 78617 cells." (PMID 28947975, 2017). "Sdc-1 interacts with insulin-like growth factor 1 receptor and integrins enabling angiogenesis and cell survival hence blocking of Sdc-1 via synstatin might result in new therapeutic approaches in cancer treatment." (PMID 28293067, 2017). "However, INSR signalling has so far been associated with adverse events that have limited the clinical success of anti-cancer strategies targeting IGF1R." (PMID 28192521, 2017). "In view of these findings, inhibitors targeting IGF-1R may serve as antitumor agents, and several of them are currently undergoing clinical trials for various types of cancer." (PMID 28046018, 2017). "In fact, heterozygous IGF1R mutations were reported in cases of intrauterine and postnatal growth restriction, but not in association with cancer." (PMID 27446805, 2016). "The IGF-1R over expression in the cancers often correlates with malignancy." (PMID 28261624, 2016). "In this study, we suggest that CD24 cell surface expression in cancer cells may predict sensitivity to anti-IGF1R therapy." (PMID 27179633, 2016).
cancer (continued). "Most available clinical data support the notion that IGF1R gene mutations constitute a very rare event and no substantial evidence links IGF1R mutations and cancer." (PMID 27446805, 2016). "Several strategies of IGF-1R inhibition, such as using monoclonalantibody, antisense oligonucleotides, and small molecule kinase inhibitors directed against IGF-1R, have been developed for cancer therapy and have shown antitumor efficacy, but their clinical responses remain to be seen." (PMID 27813495, 2016). "Antagonists of the insulin-like growth factor type-1 receptor (IGF1R) are examples of other agents which have shown limited activity in several trials; however, their development was more or less terminated after they failed in common cancers." (PMID 27990273, 2016). "IGF1R signalling is involved in resistance to cytotoxic drugs in certain cancers." (PMID 27418340, 2016). "These evidences positioned the IGF1R as a promising target for treating cancer." (PMID 27179633, 2016). "Moreover, low IGF‐1 action is relevant to humans because of its link to less cancer risk, an observation that spurred the development of IGF‐1R antagonists as a clinical cancer treatment." (PMID 26534869, 2016). "This repertoire placed IGF1R as a promising target for cancer therapy." (PMID 27179633, 2016). "Targeting multiple distinct epitopes on IGF-1R, might be an effective strategy to inhibit IGF-1R pathway in cancer." (PMID 28261624, 2016). "This suggests that, while developmental growth is mediated through the insulin-like growth factor 1 receptor (IGF-1R), IGF-II/IR-A signaling can provide an additional or alternate pathway to stimulate cell growth, allowing cancer cells to become resistant to treatments targeting the IGF-1R." (PMID 27548502, 2016). "Moreover, we demonstrate here that the IGF1R is essential for the maintenance of stem/progenitor-like cancer cells and we further demonstrate that IGF1R-KD induces in vivo differentiation of the CD24+ cells toward the CD24- phenotype." (PMID 27179633, 2016). "Our findings may be a useful step in closer understanding of IGF-1R's role in cancer and as such may contribute to development of novel targeted strategies inhibiting cancer-specific pathways." (PMID 27275536, 2016). "IGF-1R expression levels do not appear to predict IGF-1R activity, and the differential expression of signalling components in cancer cells that modulate IGF-1R activity may contribute to sensitivity/resistance to anti-IGF-1R therapies." (PMID 27472395, 2016). "Theses researches provide new evidence that IGF-1R is an important target for cancer treatment." (PMID 27813495, 2016). "Using the tumorsphere assay we demonstrated that CD24+ Mvt-1 cells possess cancer stem-like cells characteristics, and we tested whether this phenotype is IGF1R-dependent." (PMID 27179633, 2016). "Such dynamic cooperative signalling between IGF-1R and Integrins may contribute to invasiveness and metastasis of cancer cells." (PMID 27472395, 2016). "Elevated expression level of IGF-1R has been detected in multiple human cancers, including HCC." (PMID 27813495, 2016). "Increases in IGF-1R have been shown in different types of cancer, melanoma, and carcinomas." (PMID 25866791, 2015). "However, in our study, cancer cells subjected to an IGF-1R blockade appeared to have the ability to recruit macrophages and fibroblasts, which subsequently recruited VE cells." (PMID 26465273, 2015).
cancer (continued). "IGF-1R expression and activation levels generally cannot be correlated in cancer cells, suggesting that cellular proteins may modulate IGF-1R activity." (PMID 26191041, 2015). "Deregulation of IGF-1R signalling has been noted to contribute to a variety of diseases including diabetic retinopathy, diabetic nephropathy, age-related macular degeneration, cardiovascular disease, and aging and in a variety of cancers." (PMID 25866791, 2015). "The insulin-like growth factor 1 receptor (IGF-1R) may be involved in the development of resistance against conventional cancer treatment." (PMID 25680198, 2015). "The role of the IGF system and particularly IGF-1R in human cancer has been widely documented." (PMID 25906745, 2015). "Further, we hypothesized that IGF-1R inhibition might sensitize HR proficient cancers to Poly ADP ribose polymerase (PARP) inhibitors." (PMID 26510816, 2015). "Hence, DDR1 is a newly characterized adhesion receptor that regulates IGF-1R expression and signaling in cancer cells." (PMID 26191041, 2015). "This suggests that IGF1R may play a role in the EGF-MCSF cancer cell-TAM paracrine invasion pathway." (PMID 25629162, 2015). "This creates a situation whereby insulin analogues with increased affinity for IRA and/or IGF1R may increase the cancer hazard." (PMID 25848982, 2015). "In recent years, the IGF1R has been suggested to be a promising target for different human cancers." (PMID 26497207, 2015). "Targeting IGF1R by CAR T cells may represent a potential curative therapy for IGF1R+ cancer by providing several advantages over antibodies." (PMID 26173023, 2015). "Of note, two independent groups simultaneously reported in 2010 that IGF-1R undergoes nuclear translocation in human cancers, indicating that IGF-1R itself may act as a transcription factor." (PMID 25743390, 2015). "The pivotal discovery in 1993 that mouse embryonic fibroblasts derived from embryos with a targeted disruption (homologous recombination) of the IGF-1R genes, named R-cells, were refractory to transformation, set of a tidal wave of excitement in the field of cancer therapeutics." (PMID 25964779, 2015). "The IGF-1R gene has been identified as a molecular target for a number of stimulatory transcription factors and inhibitory proteins with important implications in cancer." (PMID 25906745, 2015). "Taken together, it is clear that IGF-1R expression is highly adaptable during cancer progression." (PMID 26191041, 2015). "Inhibitors of IGF1R activity are being strongly pursued for anti-cancer therapeutics." (PMID 25629162, 2015). "In addition, anti-IGF-1R therapy was shown to augment the response of certain malignant tumors to RT in preclinical settings 18,19." (PMID 25355701, 2015). "In addition to IGF1R inhibitors and mabs, IGF1R has been considered to be immunogenic and tested as a cancer vaccine." (PMID 26173023, 2015). "The IGF-1R pathway plays a major role in mediating the activation of prosurvival pathways and contributes to resistance to various anticancer therapies, including chemotherapies, radiation therapy, and molecular targeted therapies, in multiple cancer types." (PMID 26041671, 2015). "We first determined whether the IGF-1R blockade-induced cancer metastasis was mediated by the direct effects of cixutumumab on cancer cells." (PMID 26465273, 2015). "However, IGF-1R activation can also promote cell migration in both normal and cancer cells [reviewed in Ref." (PMID 26191041, 2015). "Furthermore, many studies indicate a down-regulation of IGF-1R upon cancer progression, whereas others report elevated levels in metastatic stages." (PMID 25743390, 2015). "However, combating resistance is one of the main challenges in the currently available IGF-1R inhibitor-based cancer therapies." (PMID 26515601, 2015).